MICA (MHC class I polypeptide-related sequence A)
Diseases named in the same sentence as MICA in open-access papers (continued):
Sharing a sentence is not in itself a finding about the gene and the disease.
tumor (continued). "The increased expression of MICA and MICB on CSC targets thereby enhanced NK cell mediated killing in vitro and ex vivo from both human primary tumor and patient-derived xenograft samples." (PMID 30646520, 2019). "In cancer, the interaction between membrane-bound MICA and NKG2D activates anti-tumor NK and T cell responses." (PMID 31166958, 2019). "It was demonstrated that NKG2D ligands (MICA, MICB, and ULBP) carried by tumor-derived EVs bound to the inhibitory receptor, NKG2D, on the surface of NK cells, with delivering of inhibitory signals and blocking of anti-tumor cytotoxicity of NK cells." (PMID 31680949, 2019). "In terms of cancer therapy, it is well appreciated that MICA and MICB are abundantly expressed in human tumours." (PMID 30626155, 2019). "We supported this finding by demonstrating decreased NK cell recognition and reactivity to tumour cells that were neutralised with antibodies against the NKG2DL, MICA and/or MICB." (PMID 30908480, 2019). "The interaction between NKG2D on the NK cell and NKG2DL (MICA and MICB) on the tumour cell activates NK cell anti-tumour functions." (PMID 30908480, 2019). "The previous experiments showed that VPA induces a significant increase in MICA/B and ULBP-2 surface expression and release from tumor cells of different origin." (PMID 30972064, 2019). "NK cells that were pre-treated with recombinant MICA and MICB had decreased anti-tumour functions compared with the IgG-Fc control protein." (PMID 30908480, 2019). "Both γδ T cell-subsets highly express NKG2D, the activating receptor for MICA and MICB and lyse different tumor cells in a NKG2D-dependent manner." (PMID 31555275, 2019). "For example, the antibodies, stabilizing MICA and MICB on the surface of tumor cells, were proved to enhance the cytotoxicity of NK cells." (PMID 31288857, 2019). "We further determined the expression of Bmi1, MICA/B, GATA2 and p-AMPK in the tumor tissues of different treatment group." (PMID 31088566, 2019). "Recently, a new antibody was developed to prevent the shedding of both MICA and MICB in order to restore NKG2D receptor activity and induce better killing of tumor cells by inducing antibody dependent cellular cytotoxicity (ADCC)." (PMID 30254634, 2018). "A number of microRNAs can quench the tumor response by suppressing the MHC class 1-related chain molecule A and B (MICA and MICB), which are expressed on tumor cells and are ligands of the natural killer (NK) cell activating receptor NKG2D." (PMID 30046565, 2018). "Soluble ligands for NKG2D, including MICA, have been found in serum from several types of cancer patients and, in humans, high levels of soluble NKG2D ligands generally correlate with higher tumor grade and worse prognosis." (PMID 29720199, 2018). "Unfortunately, in colorectal cancer patients, a reduction in MICA, in particular, has been found to be associated with poorer prognoses; the reason could be proteolytic shedding of the cells, which can interact with NKG2D on NK cells, preventing the NK cells from interacting with tumor cells." (PMID 29724044, 2018). "MICA and MICB can be expressed at the surface of a wide variety of tumor cells upon stress, while having a very limited expression on healthy tissues." (PMID 30400835, 2018). "In fact, in the presence of tumor-derived exosomes, NKG2D is one of the most profoundly affected NK receptors, which have MHC class I-related chain A (MICA) and B (MICB) as crucial ligands for its induction." (PMID 29515996, 2018). "In fact, a significant decrease of MICA/B expression and a marked increase of NKG2D+ tumor-infiltrating lymphocytes were observed in less-differentiated tumors with mesenchymal characteristics." (PMID 30597841, 2018). "Major histocompatibility complex (MHC) class I–related chain A (MICA) is a ligand for NKG2D, which is frequently expressed on the surface of tumor cells." (PMID 30214375, 2018).
tumor (continued). "MICA and MICB are stress-induced markers that bind to NKG2D on NK cells, thereby facilitating degranulation of NK cells and killing targeted tumor cells." (PMID 29724044, 2018). "NKG2D recognizes the structurally related ligands (NKG2DLs) MHC class I chain-related protein A (MICA), MICB, and several UL-16-binding proteins commonly overexpressed on tumor cells." (PMID 28443091, 2017). "On the other hand, downregulation of NK-activating ligands for NKG2D such as MICA and MICB and increased shedding of tumor-derived soluble MIC also impair NKG2D-mediated NK cell tumor recognition." (PMID 28620386, 2017). "We examined the transcription level of MICA using paired HCC and adjacent non-tumour liver tissues from 21 individuals with HCV." (PMID 28928439, 2017). "MICA (MHC class I chain-related protein A) is the best studied human NKG2DL, and frequent MICA expression by tumor cells and in cancer patients has been documented by many reports." (PMID 29163533, 2017). "For example, MICA and MICB are recognized by the NK cell activating receptor NKG2D, triggering cytotoxicity against the NKG2D ligand-carrying tumor cell." (PMID 27843441, 2016). "Studies found that tumor cells avoid the response of NKG2D through shedding MICA from the cell surface, and this soluble MICA hinders recognition of the MICA-expressing tumor cells, thereby impairing the anti-tumor immune response." (PMID 26909862, 2016). "Collectively, our findings suggested that SEP and 5-FU coordinated to enhance the cytolytic activity of NK cells against tumor cells by stimulating the interaction between NKG2D and MICA in vitro." (PMID 27385218, 2016). "It has been reported that MICA and MICB are heat-induced, and that excessive soluble MICA and MICB in cancer patients (shed by the tumor cells) and in pregnant women (shed by the fetal trophoblast) cause downregulation of NKG2D and relative immune suppression." (PMID 26745675, 2016). "Soluble MICA/B in circulation down-regulates NKG2D expression and disturbs NKG2D-mediated antitumor immunity, and as a result, tumor cells escape from NKG2D-mediated immuno-surveillance." (PMID 27385218, 2016). "A knockdown of HSF1 decreases the membrane expression of MICB but not that of MICA, whereas a treatment with NZ28 inhibits the expression of both, MICA and MICB on the surface of the investigated tumor cells." (PMID 25854583, 2015). "At the post-translational level, NKG2D ligands such MICA, MICB, and ULBPs were found to be cleaved from the cell surface by proteases ADAM10/17 and MMP14 and in some cases by tumor-derived exosomes." (PMID 25788898, 2015). "In contrast, NZ28 significantly reduced the MICA and MICB membrane expression (MFI) in both tumor cell lines." (PMID 25854583, 2015). "HNSCC spheroids expressed only low-to-moderate levels of membrane-bound MICA, but sMICA and TGF-β1 release steadily increased in supernatants of cultured HNSCC tumor spheroids and reached saturation levels after a few days of cultivation." (PMID 26579120, 2015). "NKG2D provides activation signals upon binding to non-classical MHC molecules of the MHC class-I chain-related molecules (MICA/B) and UL-16 binding protein (ULBP) families expressed on tumor cells." (PMID 25426120, 2014). "Our results revealed that the weak expression of MICA and MICB was correlated with worse tumor differentiation, later TNM stage, and more lymphatic invasion." (PMID 24885711, 2014). "The MHC class I chain-related sequence A (MICA) and the MHC class I chain-related sequence B (MICB) are well-characterized NKG2DLs, and play an important role in NK cell-mediated anti-tumor immune responses." (PMID 24885711, 2014). "Several stress-induced activating ligands, like MHC class I-related chain A (MICA) and B molecules (MICB), and UL16-binding proteins (ULBPs), expressed by tumor cells are recognized by the activating NKG2D receptor on NK cells." (PMID 25115382, 2014).
tumor (continued). "Major histocompatibility complex class I-related chain A and B (MICA/B) are stress-inducible ligands that bind to the immunoreceptor NKG2D and play an important role in tumor immunity." (PMID 25228093, 2014). "Recent studies showed that the increase of MICA and MICB expression on target tumor cells induced an increase in sensitivity to lysis by NK cells." (PMID 23493799, 2013). "Major histocompatibility complex class I-related chain A (MICA) and UL16 binding protein 2 (ULBP-2) are tumor cell surface ligands that bind NK cell activating receptor NKG2D, and are prevalent in malignant brain tumors." (PMID 23626949, 2013). "In conjunction with the increased MICA expression, the addition of the GSK3 inhibitor significantly enhanced NK cell-mediated cytotoxicity of tumor cells." (PMID 24391651, 2013). "NKG2D ligands, ULBP1, ULBP2, MICA, and MHC-I on tumor cells, and NKG2D, NKp44 and NKp46 on NK cells were evaluated with flow cytometry." (PMID 23937717, 2013). "Shedding of the NKG2D ligand, MICA, by chronic lymphocytic leukemia cells can be induced upon translocation of the endoplasmic reticulum-resident proteins ERp5 and GRP78 to the tumor cell surface." (PMID 24391651, 2013). "In contrast to murine NKG2D ligands, tumor-derived soluble MICA/B molecules can induce endocytosis and degradation of NKG2D on both tumor-infiltrating and peripheral-blood lymphocytes from patients with cancer." (PMID 21605422, 2011). "The recognition of the MICA and MICB ligands on tumor cells by the NKG2D receptor, found on NK cells, induces the cytotoxic activity of NK cells and the subsequent lysis of their tumor targets." (PMID 21477352, 2011). "It would be interesting to determine if the simultaneous expression of MICA, MICB and the NKG2D receptor is present in different types of virus-infected and tumor cells." (PMID 21477352, 2011). "NKG2D encodes for a lectin-related protein expressed as a homodimer and functioning as an activating receptor for ligands often expressed by tumor cells, namely, class I MHC-related molecules such as MICA, MICB, and UL16-binding proteins." (PMID 21138560, 2010). "MMPs or ADAMs can hydrolyze MICA and MICB on the surface of tumor cells into soluble molecules." (PMID 40563539, 2025). "Additionally, MICA/MICB and NKG2D are a known receptor–ligand pair expressed in tumor cells and NK cells, respectively." (PMID 40430484, 2025). "In another study, the high-affinity monoclonal antibody RDM028 targeting the α3 domains of MICA and MICB was also reported to have inhibitory effects on the exfoliation of MICA and MICB, enhance the anti-tumor activity of NK cells, and promote the interaction between MICA/B and NKG2D." (PMID 40563539, 2025). "This strategy can be used to target stress-induced ligands like MICA and MICB on tumor cells." (PMID 40226616, 2025). "Taken together, these data support that CuET stimulates i) NKG2D receptor expression on NK and T cells and ii) NKG2D ligand expression, such as MICA/B and ULBP1/2, on tumor cells, thereby facilitating immune recognition and more effective elimination of tumor cells by cytotoxic effector cells." (PMID 40013140, 2025). "Upon the binding of MICA to NKG2D, NKG2D engages with the adaptor dimer DAP10, initiating signaling activation, which promotes cell-mediated cytotoxicity, cytokine production, and the clearance of tumor cells." (PMID 40723248, 2025). "Many results suggest that high concentrations of soluble NKG2DLs may inhibit tumor immunity and NK cell activity through downregulation of NKG2D expression or proteolytic shedding of MICA/B." (PMID 38245520, 2024). "The tumor cells were stratified into two distinct groups based on their MICA expression levels: the MICA high expression group (comprising MICA+ malignant cells) and the MICA low expression group (comprising MICA− malignant cells)." (PMID 38254761, 2024).
tumor (continued). "The use of MICA-expressing oncogenic adenovirus named ICOVIR15KK-MICAMut demonstrated improved control over tumor growth compared to other viruses without MICA expression." (PMID 39055561, 2024). "MICA, a major ligand of NKG2D, is a widely utilized target in NK anti-tumor therapy." (PMID 39048814, 2024). "Moreover, in colon carcinoma and sarcoma cells, treatment with HDAC inhibitor Entinostat, a class I HDAC1 and HDAC3 inhibitor, led to increase in expression of NKG2D ligand MICA and MICB, enhancing cytotoxicity of NK cells against tumor cells." (PMID 39161385, 2024). "Additionally, Gal-3 reduces the affinity of MICA for its receptor NKG2D, and severely impairs NK cell activation, thereby promoting tumor evasion." (PMID 38793619, 2024). "Analysis of tumor growth revealed an immune protective effect of MICA not only on the growth of the primary tumor, but also on the rechallenge with CT26, suggesting the role of the endogenous adaptive immune system in the observed antitumor effect." (PMID 38180524, 2024). "HIF-1α impedes immune surveillance and natural killer (NK) cell infiltration by interfering with MHC class I polypeptide-related sequence A (MICA) and inhibiting the expression of natural cytotoxic receptors and the activator NKG2D, thereby interrupting tumor antigen recognition." (PMID 38891772, 2024). "Furthermore, we analyzed the correlation of MICA expression and NK cells & CD8+T cells infiltration in HCC tumor from the TIMER database." (PMID 36765808, 2023). "MICA/MICB are transmembrane glycoproteins that, in tumor evasion, undergo proteolytic shedding and function as a soluble decoy preventing activation through cell-membrane binding by quenching NKG2D, a receptor that, during cellular stress, gets activated and leads to cytotoxicity." (PMID 36968223, 2023). "We also found that the NKG2D receptor on the surface of the CD8+ T lymphocyte interacts with the non-canonical MHC molecule, the MicA protein present on the outer membrane of the tumor cell, and ensures that the lymphocyte recognizes thetarget cell." (PMID 36653582, 2023). "Moreover, previous studies have shown that MICA and MICB, members of the MHC-I family, are frequently highly expressed in tumor cells and can be proteolytically shedded by tumors as an important immune evasion mechanism avoiding the recognition of NK cells." (PMID 37427097, 2023). "In addition, the platelet coating on tumor cells reduces the surface expression of NKG2D ligands, including MHC class I chain–related proteins A and B(MICA and MICB) on tumor cells, impairing the “induced self” recognition of NK cells." (PMID 37153586, 2023). "Moreover, miR-125b as a tumour suppressor is commonly deregulated in cancer, while its overexpression downregulates c-Myc and IRF4 mRNA expression but upregulates MICA mRNA and protein expression." (PMID 37784183, 2023). "Meanwhile, a significantly higher IRF1 level was found in the HCC tumor cells with positive MICA expression than those with negative." (PMID 36765808, 2023). "Moreover, patients who develop autoantibodies against MICA following anti-CTLA4 immunotherapy benefitted from a reduction in soluble MICA, restoration of NK and CD8+ T cell function and enhanced tumour lysis and dendritic cell cross-presentation." (PMID 37626965, 2023). "Treatment of colon carcinoma cells with entinostat led to enhancement of acetylated histone 3 (AcH3) binding to MICA and MICB promoters, increasing their expression in a dose and time-dependent manner, resulting in higher NK cell-mediated tumor cell lysis, as compared to untreated cells." (PMID 37090711, 2023). "The increased levels of MICA and ULBP1 bound to NKG2D on NK cells and could lead to NK‐cell exhaustion before the appearance of tumor cells, and the increase in HLAE levels inhibited NKA by binding to NKG2A." (PMID 36931723, 2023).
tumor (continued). "The signature based on MICA, ULBP3, and ULBP5 could predict HCC recurrence in three independent cohorts, which was related to the levels of NK‐cell infiltration in HCC tumor tissues." (PMID 36210637, 2023). "Interestingly, in the TCGA‐LIHC and Guilin cohort, there was a significant difference in the expression of MICA, MICB, and ULBP1‐5 between HCC tumor and adjacent non‐tumor tissues." (PMID 36210637, 2023). "While there is high affinity binding to the tumor antigens MICA/MICB, not all leukemic cells express ligands of the MIC family and cannot be reached by this targeted immunotherapy." (PMID 36555547, 2022). "Our small molecule screen assay and subsequent mechanistic studies demonstrated that epigenetic modifiers enhanced the chemotaxis and cytotoxicity of γδ T cells through upregulating MICA/B, inhibiting HDAC6/7 pathway and downregulating the levels of PD‐L1 and PD‐L2 in CAFs and tumour cells." (PMID 35731974, 2022). "MICA, an important NKG2D ligand, is expressed in various tumor cells." (PMID 35309907, 2022). "Interestingly, we show that the three least targetable tumor cell lines, U87, PC3, and SK-RB-3 expressed very little MICA/B." (PMID 35119498, 2022). "Hence, blocking NKG2D-mediated Vγ9Vδ2+ T-cell recognition of tumor cells with anti-NKG2D and anti-MICA/B monoclonal antibodies inhibits tumor cell killing to varying degrees." (PMID 35880177, 2022). "In addition, using of paraffin sections from SCID mice ectopic tumor model and IHC analysis confirmed that human NKG2D ligands, MICA/B expression also increased after either HDACi/RT alone or combined treatment in the in vivo HCC model." (PMID 36185276, 2022). "Hence, we performed qRT-PCR to assess MICA/B ligand mRNA expression in the 6 days ECM-detached MCF-7 and HeLa tumor cell lines." (PMID 35323710, 2022). "In HCC, PGRN enhances the shedding of tumor cell MHC class I chain-related protein A (MICA), an innate NK and T-cell stimulatory molecule, suggesting that PGRN might represent a tumor-intrinsic factor rendering tumor cells invisible to immune elimination." (PMID 35013174, 2022). "Because the presence of MICA and MICB on tumor exosomes has been validated, thus it is likely that exosomal MICA/B might be able to alter NKG2D expression similar to their soluble counterparts." (PMID 35031075, 2022). "In a solid tumor-focused study, we have demonstrated that tumor cells are killed by NK cells in a NKG2D-dependent manner when treated with 7C6, thus indicating that inhibition of MICA/B shedding promotes NKG2D-mediated recognition of malignant cells by NK cells." (PMID 36555547, 2022). "However, in order to exert therapeutic activity, NK cells require tumor expression of ligands for activating receptors, such as MHC Class I peptide A/B (MICA/B) and ULBPs." (PMID 34926577, 2021). "Furthermore, some tumor cells also downregulate NKG2D ligands, such as MICA, on the tumor cell membrane." (PMID 34209646, 2021). "Among activating NK cell receptors, NKG2D, which recognizes stress-induced ligands MICA, MICB, and ULBP1-6 expressed on tumor cells, is one of the best-studied, but there are still some questions about the mechanisms of the impact of NKG2D ligands on NK cell function." (PMID 34835294, 2021). "Therefore, immunization with BLS-MICA induced therapeutic anti-MICA Ab that constitute a “two-in-one” strategy as they promote tumor elimination by ADCC and interfere with a tumor immune escape through scavenging of sMICA." (PMID 34394116, 2021). "Another NK cell receptor, NKG2D, though not required for mediating ADCC, is critical for NK cell activation after binding to its ligands, major histocompatibility complex (MHC) class I-related chain A and B (MICA and MICB/MICAL-1 and MICAL-2), which are overexpressed on tumor cells." (PMID 33391547, 2021). "Several lncRNAs may also interfere indirectly with NK anti-tumor activity and tumor immune escape by regulating the expression and shedding of MHC class I chain related A (MICA)." (PMID 34943820, 2021).